INS (insulin)
Diseases named in the same sentence as INS in open-access papers (continued):
Sharing a sentence is not in itself a finding about the gene and the disease.
diabetes (continued). "Next, we assessed streptozotocin-induced (STZ-induced) diabetes on C57BL/6J mice using 2 different protocols where animals were subjected to insulin-deficient hyperglycemic conditions for short-term (10 days) and long-term (2.5 months) periods." (PMID 33148881, 2020). "The proportion of patients with complications associated with diabetes mellitus (retinopathy or nephropathy) in this study was also high, and 70% were insulin users." (PMID 32656267, 2020). "R6/2 mice exhibit pancreatic inclusions associated with hyperglycemia and insulin-deficient diabetes 39,40." (PMID 32327686, 2020). "Failed compensatory insulin secretion and expansion of β-cell mass during insulin resistance are important predictors of diabetes susceptibility." (PMID 33542706, 2020). "Diabetes mellitus is a metabolic disorder that is characterized by a deficiency in insulin secretion or action resulting in hyperglycemia." (PMID 32517367, 2020). "Although insulin sensitivity is characteristic of these long-lived mutant mice, diabetes is seldom a cause of death in these stocks." (PMID 32464603, 2020). "Another limitation is the lack of individual participant data, which precluded stratifying results according to insulin use during pregnancy, family history of diabetes, and polycystic ovary syndrome which are the high risk factors for T2DM." (PMID 32405502, 2020). "Mounting evidence suggests that obesity, diabetes, and AD are linked through the disruption of neuronal insulin signaling." (PMID 31963819, 2020). "Type I DM requires prolonged and consistent exogenous insulin administration to address hyperglycemia, which can increase the risk of diabetes complications, such as retinopathy, nephropathy, neuropathy, and heart disorders." (PMID 32118053, 2020). "Dysfunction of insulin is the primary cause of diabetes; its deficiency in type 1 diabetes is induced by autoimmune destruction of β cells, and resistance to insulin results in type 2 diabetes, caused by obesity." (PMID 33240034, 2020). "A potential complication of diabetes mellitus is peripheral neuropathy with accompanying neuropathic pain and peripheral neuropathy is positively associated with insulin resistance." (PMID 32266160, 2020). "Another report using induced pluripotent stem cell (iPSC) derived from patients with neonatal diabetes carrying mutations in the insulin gene revealed that the derived insulin mutant beta-like cells exhibited reduced proliferation." (PMID 32699230, 2020). "Diabetes mellitus is an endocrinal and metabolic disease, caused by the inability of pancreas to produce required insulin and/or an inability of the body to effectively respond to insulin." (PMID 33568989, 2020). "Only obese individuals susceptible to insulin secretion deficiencies would develop diabetes because insulin resistance alone cannot trigger diabetes." (PMID 33113859, 2020). "Vitamin D deficiency has been shown to impair insulin synthesis and secretion in animal models of diabetes." (PMID 33633656, 2020). "Diabetes is a complex metabolic disorder caused by insufficient insulin action in the peripheral tissues and defective insulin secretion from the pancreatic β-cells." (PMID 32872540, 2020). "Diabetes is a metabolic disease caused by insufficient insulin secretion or insulin utilization disorders." (PMID 32575568, 2020). "There are two main types of diabetes: type 1 diabetes (T1D), with β-cell destruction and insulin deficiency, and type 2 diabetes (T2D), with progressive defect of insulin secretion on the background of insulin resistance." (PMID 33204216, 2020). "The traditional control of diabetes using transdermal insulin delivery by metal needles is generally associated with pain and potential infections." (PMID 34567719, 2020). "Medical treatment for diabetes such as insulin injections and oral hypoglycemic agents caused adverse side effects such as liver problems, lactic acidosis, and gastrointestinal problem." (PMID 32190386, 2020).
diabetes (continued). "Prior infection with adenovirus 36 (Adv36) has been associated with increased adiposity, improved insulin sensitivity, and a lower prevalence of diabetes." (PMID 32415247, 2020). "The most common clinical presentation described in the literature is the development of diabetes with persistent hyperglycemia despite the use of very high doses of insulin, demonstrating severe insulin resistance, associated with significant weight loss." (PMID 32813762, 2020). "OP exposure indicated risk of diabetes and insulin, glycaemia, adiponectin, triglycerides, and TNF-α dysregulations." (PMID 33194944, 2020). "Diabetes mellitus (DM) is a metabolic disease associated with hyperglycemia due to abnormalities of insulin secretion, action, or both." (PMID 32337271, 2020). "The most predominant form of diabetes, type 2 diabetes mellitus, affects millions of persons worldwide and is typically as a result of deficiency of insulin action in peripheral tissues." (PMID 33133220, 2020). "Diabetes mellitus is one of the most common metabolic diseases in the developed world, and is associated either with the impaired secretion of insulin or with the resistance of cells to the actions of this hormone (type I and type II diabetes, respectively)." (PMID 32911736, 2020). "Type 2 diabetes mellitus (T2DM) occurs from the progressive loss of insulin secretion from the β-cells in the pancreas and/or increasing insulin resistance." (PMID 33126498, 2020). "Diabetes mellitus is a heterogeneous and chronic disease, characterized by hyperglycemia caused by an absolute or relative deficiency in insulin secretion or action, resulting in impaired function in carbohydrate, lipid, and protein metabolism." (PMID 33383693, 2020). "Of the 13 subjects, 11 had diabetes mellitus with a mean age at onset of 15.5 ± 12.7 years (7/11 treated with insulin); 2 patients had diabetes insipidus and 6 had hearing loss." (PMID 32179840, 2020). "CDKAL1 variants have been shown to predict the development of diabetes in individuals with impaired insulin secretion, which suggests potential synergistic effects between different risk factors." (PMID 32764395, 2020). "A magnesium-deficient diet caused a significant impairment of insulin-mediated glucose uptake in sheep, while magnesium supplementation delayed the development of diabetes in a rat model of diabetes." (PMID 33396570, 2020). "The fourth main finding of this study is that the IDF definition better predicted elevated fasting insulin, a risk factor for diabetes, than did the ATP III definition." (PMID 33260754, 2020). "Diabetes mellitus (DM) is a diversely complicated disease of insulin dysfunction often associated with dreadful repercussion by hyperglycemia, hypoinsulinemia, and glycosuria." (PMID 32792955, 2020). "Diabetes mellitus (DM) is a metabolic disorder caused by a defect in the insulin secretion and/or action, leading to chronic hyperglycemia." (PMID 31979346, 2020). "We further analyzed the association between serum GPLD1 levels with glycemic parameters and circulating insulin levels because GPLD1 is well-known to be associated with diabetes." (PMID 32467736, 2020). "The association between diabetes and breast cancer supports the effect of insulin and IGF-1 as a mitogen and also its influences on estrogen hormone levels." (PMID 32528752, 2020). "F. krishnae is a new source of the two phytosterols (CA+24-MCA), which exert antidiabetes activity by protecting beta cells from glucotoxicity associated with diabetes, enhancing beta cell population and normalizing insulin release from pancreatic beta cells." (PMID 32584888, 2020). "Insulin deregulation are connected with diabetes, obesity, cardiovascular disease, and hypertension and abnormal neural insulin signaling pathways are linked with various neurodegenerative diseases and learning memory deficits." (PMID 32824367, 2020).
diabetes (continued). "The study also provides insight into insulin-mediated processes and their underlying mechanisms, which is of great interest for human health owing to its essential roles in diabetes, metabolism, aging, and cancer." (PMID 32457793, 2020). "As diabetes is a metabolic disease causing serious long-term consequences, it is essential to understand the process of insulin secretion to find an effective treatment." (PMID 33905469, 2020). "Scenarios simulating the impact of scaling back these interventions showed that insulin sensitivity decreased significantly, increasing the risk for early development of diabetes mellitus." (PMID 32475837, 2020). "Patients with diabetes are usually coupled with insulin reduction results from pancreatic β-cell deficiency or substantial β-cell loss." (PMID 32345350, 2020). "The alteration of these parameters has also been associated with arterial hypertension, central obesity, hepatic insulin sensitivity, and increased diabetes risk." (PMID 32932674, 2020). "This reflects the association of exogenous insulin treatment with the severity of an impaired glucose tolerance, also predictive of higher diabetes progression rate later in life." (PMID 32725280, 2020). "Insulin resistance (IR), caused by impaired insulin signal and decreased insulin sensitivity, is generally responsible for the pathophysiology of type 2 diabetes mellitus (T2DM)." (PMID 33240683, 2020). "Diabetes is a chronic disease characterized by chronic hyperglycemia, absolute or relative deficiency of insulin secretion, and chronic inflammation." (PMID 32629649, 2020). "Diabetes is characterized by hyperglycemia caused by defects in secretion and/or insulin signaling, which is directly associated with alterations in the glucose uptake and signaling of insulin-dependent glucose transporters (GLUT)." (PMID 33203103, 2020). "With regard to the cost of insulin in the United States, a working group of the American Diabetes Association has extensively discussed this issue." (PMID 32396624, 2020). "The proposed causes of diabetes in HH include decreased pancreatic β-cell function secondary to apoptosis and increased ROS, decreased insulin secretory capacity, and decreased sensitivity to glucose-induced insulin secretion." (PMID 32121273, 2020). "Both genetic and environmental factors interact in the development of diabetes, as genetic predisposition increases the susceptibility of insulin sensitivity and pancreatic β-cells towards detrimental environmental factors, such as obesity." (PMID 33261162, 2020). "Diabetes is a chronic metabolic disease characterized by hyperglycemia caused by a defect in insulin secretion, insulin function, or both." (PMID 32539861, 2020). "Diabetes mellitus is a complex metabolic disorder which is associated with insulin resistance, insulin signaling impairment, β-cell dysfunction, abnormal glucose and lipid metabolisms, inflammation and mitochondrial oxidative stress." (PMID 33086679, 2020). "Diabetes is characterized by a high level of glucose in the bloodstream caused by insufficient insulin secretion or insulin resistance." (PMID 32133389, 2020). "PEDF is not only associated with insulin sensitivity and diabetes mellitus but also with its complications." (PMID 32785102, 2020). "Understandably PGC-1α is also linked with type 2 diabetes mellitus in the pancreas where B-cells are supposed to manufacture and secret insulin." (PMID 33022986, 2020). "Insulin resistance leads to decreased uptake of insulin and a reduced sensitivity of IRs in the brain and is linked to cognitive decline in diabetes, AD, and PD." (PMID 33100956, 2020). "When participants were asked why they restricted insulin, three main themes were identified: weight loss, a hate of diabetes and self-harm." (PMID 32967730, 2020). "Increased prostate size and BPH surgery have strong association with the diagnosis of diabetes and increased serum insulin fasting plasma glucose level." (PMID 32375790, 2020).
diabetes (continued). "There are multiple potential causes for our failure to observe impaired insulin secretion and diabetes in β-R1183W and iβ-R1183W mice." (PMID 34368464, 2020). "Long term human insulin and insulin analogue use contributes to diabetes-associated cancers through activation of insulin receptors." (PMID 32498358, 2020). "Ninety percent of the patients with diabetes suffer from type 2 diabetes, and one of the main causes of this disease is reduced insulin secretion due to pancreatic β-cell dysfunction." (PMID 32825285, 2020). "A non-Euro Caucasian origin, late institution of GDM treatment and the need for insulin therapy were associated with failure of diabetes management." (PMID 32346630, 2020). "Diabetes is a complex chronic disease that causes glucose induction, insulin secretion disorders, autoimmune-mediated beta cell destruction, or inadequate compensation of insulin secretion for insulin resistance." (PMID 33202817, 2020). "Insulin treatment lowered blood and detrusor tissue glucose levels, which reversed a majority of the changes in metabolism caused by diabetes." (PMID 33200530, 2020). "Polish Diabetes Association as well as European and US guidelines recommend insulin as an option after life style modification and metformin to bring glycated haemoglobin (HbA1c) below a general target of 7% (53 mmol/mol)." (PMID 32071879, 2020). "Even if typically low, this insulin production is very important since it has been clinically associated with longer periods of remission (i.e., a honeymoon phase) and less severe diabetes-related vascular complications." (PMID 31940853, 2020). "Preservation of even small amounts of residual endogenous insulin production can improve glucose metabolism, reduce risk of hypoglycaemia and diabetes associated vascular complications, such as retinopathy, nephropathy and neuropathy." (PMID 32399500, 2020). "On the other hand, ARL6IP1 and PSMC6 have been associated with insulin synthesis and pathology of diabetes, respectively." (PMID 32296077, 2020). "Insulin resistance is defined by a reduced response to insulin in tissues that is associated with adverse health risks, including diabetes, coronary heart disease, reduced cognitive function, and reduced renal function." (PMID 31992297, 2020). "Pregnancy, breast feeding, plan for pregnancy, use of antiobesity medication or medication/insulin for diabetes, surgery for weight loss, and use of the antidepressant sertraline." (PMID 32706724, 2020). "Although the mechanism is not well studied, it has been proposed as a stronger predictor of insulin sensitivity and a lower risk of diabetes." (PMID 33299523, 2020). "Obesity is a risk factor for glucose intolerance leading to diabetes, which is first detected as increased circulating insulin concentrations followed by increased fasting blood glucose levels." (PMID 32379797, 2020). "Effects of bariatric surgery on weight loss, daily insulin requirements and glycosylated hemoglobin in patients with obesity and type 1 diabetes mellitus." (PMID 33071965, 2020). "Levels of lysine, tryptophan, valine, and other amino acids have also been variably correlated with markers of insulin resistance, insulin secretion, and/or risk of diabetes and CVD." (PMID 33255565, 2020). "Diabetes mellitus is a metabolic syndrome where pancreatic β-cells fail to meet the body’s need for insulin with resultant hyperglycaemia and increased risk of diabetic complications." (PMID 32517842, 2020). "Promising effects of olive polyphenols were also observed on glycemia and diabetes and it was shown that supplementation with an olive leaf extract was associated with significant lowering of HbA1c and fasting plasma insulin levels." (PMID 32942738, 2020). "In our laboratory, we continue to examine the importance of variations in insulin clearance rates to diabetes risk, and mechanisms underlying the variations in clearance across different populations." (PMID 33658981, 2020).
diabetes (continued). "Due to their differential regulation in T2D-associated tissues along with their association with insulin secretion-related traits, our insilico analysis points towards a major role of these genes in diabetes pathophysiology, with high confidence." (PMID 32294959, 2020). "Other mechanisms associated with vitamin D and diabetes include enhancement of insulin responsiveness for glucose transport, and improvement of systemic inflammation." (PMID 31937856, 2020). "With regard to diabetes treatment, we found that patients treated with insulin had a greater mortality risk than those treated with oral glucose-lowering medications or combination therapy." (PMID 32962295, 2020). "This rare syndrome has difficult-to-control diabetes, even with high doses of insulin, and it is usually associated with autoimmune diseases." (PMID 32813762, 2020). "VAT is an independent predictor of endogenous insulin sensitivity and glucose tolerance; this, in turn, suggests that reducing VAT is crucial for improving insulin sensitivity and preventing diabetes in high-risk individuals." (PMID 33126534, 2020). "All types of insulin are provided for free funded by the Sudan Childhood Diabetes Association except insulin glargine." (PMID 33299891, 2020). "Several genes associated with insulin function or glucose metabolism and/or linked to diabetes were identified as repositioning concomitantly with a change in expression." (PMID 33330474, 2020). "RBP4 is secreted from GLUT4-deficient adipose tissue in mice and elevated in the serum of insulin-resistant and diabetic subjects, as well as in first-degree relatives with a high risk of developing diabetes." (PMID 32591906, 2020). "In contrast, SphK2 can be pathogenic, as systemic loss of Sphk2 ameliorates diabetes by preventing pancreatic β-cell death and improves insulin sensitivity in aged mice by promoting lipolysis in adipose tissue." (PMID 32917816, 2020). "Db/db mice showed age-related increases in body weight, fasting plasma glucose, and plasma 8-isoprostane, with deterioration in glycemic control and insulin secretion reflecting the progression of metabolic dysfunction associated with diabetes." (PMID 32858910, 2020). "Defective insulin secretion by pancreatic β-cells and insulin sensitivity are the main causes of diabetes mellitus type 2." (PMID 32503113, 2020). "Most dogs with diabetes have a deficiency in the production of insulin, a hormone produced by the pancreas that reduces blood sugar, due to a loss of the insulin producing cells in the pancreas (β-cells)." (PMID 33323126, 2020). "After adjusting for age, sex, education status, duration of diabetes, current smoking, BMI, HbA1c, dyslipidemia, systolic blood pressure and insulin therapy, the associations remained." (PMID 32571335, 2020). "Vaspin has also been reported to be associated with insulin regulation and the development of DM, and it has been noted as potential novel biomarker of the early prediction or diagnosis of certain diabetes types." (PMID 33050209, 2020). "Diabetes mellitus occurs due to the loss or impaired function of insulin-secreting pancreatic beta cells." (PMID 31979403, 2020). "Fermented dairy product intake was associated with a lower risk of developing diabetes by the influence on intestinal microbiota and, thereby, on the insulin sensitivity of tissues and glucose tolerance." (PMID 33202986, 2020). "Diabetes mellitus describes a group of metabolic disorders characterized by hyperglycemia due to the absolute or relative insufficiency of insulin production or actions caused by a combination of genetic and environmental factors." (PMID 33553168, 2020). "The aim was to investigate the relationship between psoas muscle volume (PMV) and diabetes in individuals after pancreatitis, as well as its associations with ectopic fat phenotypes and insulin traits." (PMID 32630360, 2020).